CD4 (CD4 molecule)
Diseases named in the same sentence as CD4 in open-access papers (continued):
Sharing a sentence is not in itself a finding about the gene and the disease.
colitis (continued). "Similarly, CD4+CD25+ Treg cells transferred into hosts ameliorated colitis symptoms." (PMID 35967466, 2022). "Therefore, the reduced number of naïve CD4+ cells and defective differentiation into RORγt+ Treg cells might be reasons why Rap1KO mice develop spontaneous colitis." (PMID 35246619, 2022). "Given metabolism plays an important role in CD4+ cells differentiation, we hypothesized that S. japonicum eggs might regulate Treg/Th17 through modulating metabolism in the murine experimental colitis." (PMID 36304936, 2022). "In addition, the frequencies of CD4+ T cells in the splenocytes of DSS-induced colitis mice were also significantly decreased compared to normal control mice (11.30 ± 1.92% vs. 29.90 ± 4.14%, p < 0.01) or normal mice treated with T. halophilus (11.30 ± 1.92% vs. 28.57 ± 8.81%, p < 0.01)." (PMID 35741032, 2022). "However, TCR-Tg CD4+ T cells, i.e., Flagellin-specific CD4+ Tg (Cbir) T cells, induce experimental colitis upon the transfer into lymphopenic mice, while the administration of Treg-inducing Bifidobacterium bifidum ameliorates the colitis by inducing the generation of Cbir Treg cells." (PMID 36310871, 2022). "Mice deficient in CD4 were not protected from DNBS-induced colitis by infection with H. diminuta." (PMID 36558772, 2022). "In CD4+ T-cell-specific Mettl3 KO mice, the proportion of naïve cells was higher, while the proportion of activating CD4+ T cells was lower than that in WT mice, and Mettl3 KO mice developed spontaneous colitis, indicating that m6A helped to keep naïve cells quiescent." (PMID 36225914, 2022). "In addition, IL-6R signaling in T cells is a prerequisite for induction of T cell mediated colitis since its blockade has been shown to abrogate proliferation of CD4+ or CD8+ T cells, IFNγ production and induction of colitis in models of T cell transfer colitis." (PMID 35514976, 2022). "Therefore, we hypothesized that IFN-γ might be required for CD4+ CTL generation contributing to colitis development in R23FR mice and R23FR → Rag transfer mice." (PMID 35468944, 2022). "Additionally, in the DSS-induced colitis model, it was discovered that the intravenous injection of P. gingivalis extract-stimulated CD4+ T cells aggravated the inflammatory response and increased the Th17/Treg ratio in the colon and lamina propria lymphocytes." (PMID 36467726, 2022). "To clarify whether GPR65 modulates mucosal CD4+ T cell immune responses and promotes the development of colitis, we constructed mice with CD4+ T cell‐specific knockout of Gpr65 gene (Gpr65ΔCD4 mice) and investigated the potential role of GPR65 in modulating CD4+ T cell activation during colitis." (PMID 35343079, 2022). "To further define the key role played by Foxp3+CD4+Treg cells in the exacerbated inflammatory response of Lgals1−/− mice to DSS-induced colitis, we assessed whether adoptive transfer of WT Foxp3+CD4+Treg cells could reverse the enhanced inflammatory response observed in colitic Lgals1−/− mice." (PMID 34262567, 2021). "However, the increased expression of CTLA4 was observed only in CD4+Foxp3+ T cells in colitis." (PMID 34336843, 2021). "In general, colitis was significantly induced irrespective whether WT or Tec−/− naïve CD4+ T cell were transferred as revealed by transmural infiltration with immune cells, epithelial cell hyperplasia, loss of goblet cells, crypt abscesses, and focal erosions." (PMID 35003062, 2021). "Hence, hypoxia might work to convert CD4 cells to Treg cells to inducing immune resistance, which might be one of the reasons that Treg increases in hypoxia induced colitis." (PMID 34666625, 2021). "Pathogenesis can be impacted by background levels of colitis as evidenced in elite controller macaques and African Green Monkeys (AGM) where administration of DSS resulted in increased viral loads and increased viral loads with loss of mucosal CD4+ T cells, respectively." (PMID 33970966, 2021).
colitis (continued). "The adaptive cell transferred model (e.g., CD4+CD45RBhigh T cells) is one of the models to mimic chronic colitis in which naive T cells from immunoactivity mice are transferred to T - and B-deficient hosts (e.g., Rag1/2 -/- or SCID mice) to induce colonic inflammation." (PMID 34956195, 2021). "However, whether MHC class II expression by IECs was insufficient to induce T‐cell transfer colitis due to their inability to activate naïve CD4+ T cells and/or due to the preferential induction of Treg cells or anergy was not determined." (PMID 32966619, 2021). "Because we saw an increase in CD4 T cell IFNγ production 24 h-post IL-12 stimulation in vitro, and the T cell transfer model of colitis induces chronic inflammation over several weeks, we hypothesized that Plac8’s impact on CD4 T cell IFNγ may be limited to models of acute inflammation." (PMID 32639988, 2020). "Pharmacological activation of PPARγ in a T cell-transfer colitis model resulted in increased colonic Tregs and decreased Th17 cells in the gut mucosa, whereas deletion of PPARγ in CD4+ T cells impaired mucosal Tregs and enhanced colitogenic Th17 responses in mice with CD4+ T cell-induced colitis." (PMID 32403220, 2020). "The use of PD-L1 blocking mAb in this model prevented the development of experimental colitis in association with the decreased expansion of pathogenic T cells and downregulated inflammatory cytokine production (i.e., IFN-γ, TNF-α) by lamina propria CD4+ T cells." (PMID 33271941, 2020). "Therefore, we focused our study on whether IL-17 in the CD4 conditional TTP KO mice played a role in DSS-induced colitis by administering IL-17 neutralization Ab only to KO mice." (PMID 32922402, 2020). "In addition, the frequency of CD4+ICOS+ T cells was also shown to be unexpectedly elevated in non-tumor tissues during treatment with CTLA-4 antibody, causing immune-related adverse events, such as colitis, which should be improved in the future." (PMID 32983168, 2020). "In addition, a previous study has also reported that MG-132 could alleviate the experimental colitis in mice via mediating the immunoinhibitory effects on CD4+ T cells." (PMID 33488293, 2020). "Similar to lymphocytes from integrin β7 knock-out (KO) mice, lymphocytes from KI mice showed significantly deficient homing to the GALT, and CD4+CD45RBhigh T cells from KI mice could not induce colitis in a T cell transfer model." (PMID 32522281, 2020). "Importantly, adoptive transfer of ManLAM‐induced B10 cells alleviated the pathological symptoms and intestinal inflammation in the mice with colitis, demonstrating that B10 cells alone could contribute to reversing the unbalance of CD4+ T cells." (PMID 31657484, 2020). "To further test whether the colitis in CD4-Cre+/TgMettl14FL/FL conditional knockout mice was due to dysfunctional Treg cells, we adoptively transferred WT Treg cells into the CD4-Cre+/TgMettl14FL/FL conditional knockout mice to determine whether the colitis phenotype could be attenuated." (PMID 32634481, 2020). "Indeed, compared to WT Treg, Maf-deficient Treg do not control the development of colitis induced by the transfer of naïve CD4+ T cells into Rag1−/− mice." (PMID 30992496, 2019). "A recent study has reported that IL-18Rα-deficient CD4+ T cells induced comparable intestinal pathology to WT CD4+T cells, concluding that IL-18-dependent cytokine induced activation of these cells is not critical for the development of T-cell-induced colitis." (PMID 31379813, 2019). "Thus, we utilized a T cell transfer model of colitis to investigate whether ASC has an intrinsic role in CD4+ T cells in intestinal inflammation." (PMID 31379813, 2019). "Importantly, we showed that apoptotic cell-derived EVs suppressed experimental colitis and ameliorated the gut inflammation in CD4+CD45RBhi adoptive transfer colitis model in mice by inhibiting IFN-γ+ inflammatory T cells and enhancing Tregs in a TGFβ-dependent manner." (PMID 30971739, 2019).
colitis (continued). "Furthermore, adoptive transfer of CD4+CD25+ Treg cures established CD4+CD45RBhi transfer colitis." (PMID 31886308, 2019). "Indeed, although the injury to colonic epithelium produced by DSS exposure is the first step leading to recruitment of innate immune cells, TNBS-induced colitis, triggered by haptenization of colonic tissue proteins, is considered primarily based on the activation of CD4+ Th1-mediated responses." (PMID 31297055, 2019). "In turn, an in-depth study of ILC and T cells in the CD4 T cell transfer colitis model, in which the adaptive immune compartment contributes significantly, has shed a more nuanced light on the contribution of innate and adaptive immune cells to colitis development." (PMID 29948108, 2018). "Thus, Alpk1 deficiency in the absence of a strong microbial driver does not appear to significantly impact CD4+ T-cell differentiation or susceptibility to T-cell-driven colitis." (PMID 30228258, 2018). "Therefore, Ifng−/− CD4 CD45RBhi T cells were transferred into Rag1−/−Ifng−/− mice for colitis induction and recipient mice were treated with either isotype control antibody or neutralizing antibodies against IL17A and against IL17F twice a week for the duration of the experiment." (PMID 29416538, 2018). "TNBS-induced models of colitis, typical for Crohn’s disease, result in inadequate cell-mediated immune response, and acute Th1 inflammation, which includes a dense colonic tissue infiltration by cluster of differentiation 4 (CD4) T cells, and the release of numerous potent pro-inflammatory agents." (PMID 29865176, 2018). "Previously, our laboratory reported that Cd4-Cre mediated deletion of Pak2 in T cells resulted in a block in the development of thymic-derived and peripherally induced regulatory T cells (Tregs) coupled with the onset of spontaneous colitis, suggestive of a break in peripheral tolerance." (PMID 29213081, 2017). "Additionally, IFN-γ-producing CD4+ T cells play a substantial role in CS-induced colitis." (PMID 29163466, 2017). "Furthermore, it has been observed in a CD4+ T-cell-dependent Severe combined immunodeficiency (SCID) transfer model of colitis that pretreatment of donor mice with CpG completely abolished colitis development in SCID recipients in a CpG–TLR9-mediated modulation of T-cell function." (PMID 26925061, 2016). "Therefore, an increase in iTregs was not responsible for the reduction of colitis after transfer of TNFR2-deficient naïve CD4 cells." (PMID 27601345, 2016). "Taken together, the present results indicate that CD4+T cells play an important role in shaping the immune response during development of colitis and that attenuation of Th1 and Th17 responses by SBI could represent a significant step forward in the treatment of IBD." (PMID 27139220, 2016). "RELM-β’s ability to drive CD4+ T cell recruitment to the gut may in part explain its complicated effects during parasite infections, as well as its worsening effect on several models of colitis." (PMID 26285214, 2015). "Collectively, these results indicate the biological function of RELM-β may be context dependent, while our findings suggest its impact may reflect whether recruitment of CD4+ T cells to the intestine provides protection within the specific model tested, or alternatively, simply worsens colitis." (PMID 26285214, 2015). "Next, to test whether there was any defect when transferred to an inflammatory environment, we performed transfer colitis experiments, analyzing control or Itgb8 KO Treg cells transferred to colitic Rag2−/− mice that had received naive CD4+ T cells 2 weeks earlier." (PMID 25979421, 2015). "Thus, the expanded CD11clowCD45RB+ DCs suppressed colitis induction by CD4+ CD25− T cells in vivo." (PMID 26024301, 2015).
colitis (continued). "To further test whether the catalytic activity conferred by immunosubunits plays an essential role in CD4+ T-cell function and to distinguish between the role of immunosubunits in effector T-cells versus inflamed tissue, we used a T-cell transfer-induced colitis model." (PMID 24740379, 2014). "However, the paper presented other puzzling data indicating that A2AR-deficient CD4+ CD45RBlow cells were not as effective as wild-type CD4+ CD45RBlow cells in preventing colitis." (PMID 25071765, 2014). "Importantly, in the setting of IBD, CD80, but not CD86 blockade prevented CD4+ T cells with pathogenic potential to induce colitis in mice." (PMID 25505551, 2014). "In contrast, pioglitazone-treated mice not only recovered from colitis and its associated weight loss, but also showed a switch from a predominant Th17 into an iTreg phenotype characterized by increased expression of FOXP3 and decreased IL17-A and RORγt in CD4+ T cells of the colonic LP and MLN." (PMID 23592971, 2013). "To assess whether T cell intrinsic Nod2 regulates the function of T cells in the induction or prevention of colitis, we transferred Rag1-/- recipient mice with naive CD4+CD45RBhigh and activated/memory CD4+CD45RBlow T cells isolated from NOD2-/- or C57BL/6 mice." (PMID 24324812, 2013). "It has been proposed that NOD2-/- mice were highly sensitive to Toxoplasma gondii infection and that transfer of naive CD4+CD45RBhigh Nod2 deficient T cells into Rag1-/- recipient mice failed to induce colitis due to a T cell intrinsic defect in proliferation and Th1 differentiation." (PMID 24324812, 2013). "Notably, rapamycin treatment in CD4+ T-cell transfer model of colitis increases the differentiation of Th1 cells in mesenteric lymph nodes, possibly due to both T-cell intrinsic deviation to Th1 development and the increased production of IL-12 from APCs in the absence of PI3K-Akt-mTORC1 pathway." (PMID 23383714, 2013). "Indeed, an initial report suggested that T cell intrinsic NOD2 was important for CD4 T cell-dependent IFNγ responses to control Toxiplasma gondii in mice as well as for induction of colitis in an adoptive transfer model in which WT or NOD2−/− CD4 T cells were transferred into RAG−/− mice." (PMID 23405246, 2013). "In a colitis model, mesenteric B cells were capable of reducing CD4+ T cell-dependent colon inflammation and mesenteric CD23hi B cells of H. polygyrus-infected mice were capable of inhibiting inflammation both in an EAE model and in an HDM-specific AAI model via an unknown mechanism." (PMID 22347409, 2012). "Moreover, more CD4+ T lymphocytes were activated (CD4+ CD69+) in the colitis + HFD animals." (PMID 22073943, 2011). "Apart from these possible epithelial cell-mediated mechanisms we could identify a CpG/TLR9-mediated modulation of T-cell function in the CD4+ T-cell-dependent SCID transfer model of colitis in which colitis is induced in SCID recipients by adoptively transferred CD4+CD62L+ cells." (PMID 21188217, 2010). "Furthermore, transfer of naive T cells to Il23a−/−Rag1−/− mice fails to elicit colitis and is associated with an increase in the frequency of CD4+Foxp3+ cells in the intestine." (PMID 18400195, 2008). "So CD4+ TRM cells mainly play a proinflammatory role in UC, depletion of these cells in mice with transfer colitis resulted in significant alleviation of colitis flare-ups." (PMID 40124381, 2025). "Thus, in the chronic colitis state, PD−1 expression may not merely reflect CD4+ T cell exhaustion but may instead be associated with the long−term inflammatory nature of the disease." (PMID 40702356, 2025). "In a transfer colitis mouse model, which is achieved by injection of anti-CEA CAR CD4+ Teffs, suppressive effects and inhibitory effects on abdominal accumulation of the anti-CAR CD4+ Teffs were achieved by treatment with CEA-specific CAR Tregs." (PMID 41235222, 2025).
colitis (continued). "Conventional murine CD4 cells were activated ex vivo and injected into RAG-/- mice to induce colitis, along with simultaneous injection of Tregs that had been treated during differentiation with either vehicle or 3DZA." (PMID 40720256, 2025). "This PET tracer was used to visualize the distribution of CD4+ T cells in the abdominal region and lymphoid organs of mice with DSS-induced colitis." (PMID 39747850, 2025). "Together, our data show that the abnormal mitochondrial phenotype of CD4+ and CD8+ T cells in the colon during chronic DSS-induced colitis is resolved during the remission phase." (PMID 41007657, 2025). "(H) Statistical analysis of the percentage CD4+ FOXP3+ Treg cell in the spleen, mesenteric lymph nodes, and colon 6 weeks after colitis induction (n = 5)." (PMID 40183773, 2025). "Colonic CD4+ T cells isolated from normal control rats and TNBS-induced colitis rats were seeded into the lower chamber of a Transwell system and treated with either control siRNA or si-Ccl1-3 for 24 h." (PMID 40331987, 2025). "On top of this model, transfer of Tregs in vivo ameliorated colitis and IEC barrier disruption in the naive CD4+ T cell transfer model, but Fut7-knockdown Tregs cannot do so." (PMID 41398516, 2025). "First, although ERAP1+/− mice showed heightened colitis severity and altered immune cell profiles, the precise molecular mechanisms by which partial ERAP1 deficiency influences specific immune pathways (e.g., neutrophil activation, DC maturation, CD4+ T cell function) remain unclear." (PMID 40977735, 2025). "Flow cytometry showed that DSS-induced colitis increased T lymphocytes (CD3+), helper T cell (CD3+CD4+), and cytotoxic T cell (CD3+CD8+) proportions in the blood, indicating systemic T cell activation." (PMID 40545549, 2025). "Besides, Nat10-deficient naïve CD4+ T cells failed to induce adoptive transfer colitis." (PMID 40038243, 2025). "It is believed that CD4+ T cell‐mediated inflammation acts a key part in the IBD development and experimental colitis." (PMID 40887825, 2025). "The transfer of CD4+CD25- T cells from Foxp3creCREBfl/fl ROSARFP mice and from VAVcreCREBfl/fl prevented the development of colitis and resulted in enhanced accumulation of RFP+ Tregs in different organs." (PMID 40777015, 2025). "In this study, we identified CD4+Notch2+Foxp3lo T cells in the spinal cords of mice with experimental autoimmune encephalomyelitis (EAE), dextran sodium sulfate−induced colitis model mice, and patients with ulcerative colitis as immune regulatory cells." (PMID 40702356, 2025). "The proportion of CD4+ T cells in the mesenteric lymph nodes (mLN) was markedly reduced in mice treated with DSS during both the acute and chronic phases of colitis." (PMID 40977735, 2025). "We identified Notch2−expressing CD4+ T cells in the spinal cords of mice with EAE and the colons of colitis model mice and noted that these cells expressed low levels of Foxp3 in a manner dependent on the EAE phase." (PMID 40702356, 2025). "Increased colitis severity and stronger T helper 17 (Th17) responses, production of TNF and IFNγ by CD4+ T cells." (PMID 40860650, 2025). "For instance, in colitis tissue, the knockout of BMAL1 in PD-L1+ regulatory B cells inhibited the transcription of IL-33, resulting in the death of CD4+ T cells." (PMID 38607733, 2024). "For instance, rutin has been reported to reduce the proportion of CD4+T and CD8+T lymphocytes in colitis mice, exerting a protective effect against DSS-induced colitis." (PMID 38397562, 2024). "TNBS administration induces transmural colitis that is driven by a TH1-mediated immune response, which is characterized by the infiltration of CD4+ cells, neutrophils, and macrophages into the lamina propria and the secretion of cytokines." (PMID 39861081, 2024). "We also investigated the in vivo efficacy of these antagonists in experimental colitis by using dextran sulfate sodium (DSS) and the transfer of CD4+CD45RBhigh T cells to induce intestinal inflammation." (PMID 38713616, 2024).